NOTCH1 (notch receptor 1)
Diseases named in the same sentence as NOTCH1 in open-access papers (continued):
Sharing a sentence is not in itself a finding about the gene and the disease.
non-Hodgkin lymphoma (1 paper, 2019). Distinct from Hodgkin lymphoma both morphologically and biologically, non-Hodgkin lymphoma (NHL) is characterized by the absence of Reed-Sternberg cells, can occur at any age, and usually presents as a localized or generalized lymphadenopathy associated with fever and weight loss. "In Non-Hodgkin lymphomas, only little is known about the dependency of Notch1 signaling activation upon a certain ligand." (PMID 31676012, 2019).
pancreatic NETs (1 paper, 2016). "Studies in BON1 cells transiently overexpressing Notch1 NICD resulted in growth suppression, dose-dependent increases in Hes1, and a decrease in NET markers, confirming the tumor-suppressor function of Notch1 signaling in pancreatic NETs." (PMID 27148486, 2016).
Parkinson (1 paper, 2024). "Considering that the phenotypes of Rbm24 deletion exhibit Parkinson-like features in the SVZ-OB pathway, this study further explored the relevance of Rbm24/Notch1 signaling in PD." (PMID 39113792, 2024).
pemphigus vulgaris (1 paper, 2022). Pemphigus is a group of chronic autoimmune skin diseases characterized by blister formations on the outer layer of the skin and the mucous membranes. "The decreased level of NOTCH1 was related to the oxidative stress of keratinocytes, which contributed to the disease activity of pemphigus vulgaris." (PMID 36553065, 2022).
penile tumors (1 paper, 2025). "NOTCH1 mutations, frequently reported in HPV-negative penile tumors, were also observed." (PMID 41395625, 2025).
pericardial effusion (1 paper, 2013). Fluid collection within the pericardial sac, usually due to inflammation. "We show that endocardial-specific Notch1 or Jagged1 knockout embryos are embryonic lethal and they die around E11.5 with pericardial effusion." (PMID 23560082, 2013).
pituitary adenomas (1 paper, 2017). "In human pituitary adenomas we showed NOTCH1-4 receptors, JAGGED1 ligand and HES1 target gene expression with positive correlations between NOTCH1,2,4 and HES1, and NOTCH3 and JAGGED1 denoting Notch system activation in a subset of tumors." (PMID 28915655, 2017).
Pleural effusion (1 paper, 2025). The presence of an excessive amount of fluid in the pleural cavity. "An additional comprehensive review of chromosomal abnormalities associated with fetal pleural effusions did not identify NOTCH1 pathogenic variant." (PMID 40926891, 2025).
primary central nervous system lymphoma (1 paper, 2021). A non-Hodgkin or Hodgkin lymphoma that arises in the brain or spinal cord as a primary lesion. "There are two other phase II studies that are completed in patients with R/R primary central nervous system lymphoma (PCNSL) and advanced lymphoma and HNSCC harboring NOTCH1 loss of function mutations." (PMID 33801659, 2021).
Prolactinomas (1 paper, 2017). "Prolactinomas harbored by lacDrd2KO mice expressed high levels of NOTCH1 active domain and reduced Hes1." (PMID 28915655, 2017). "On the other hand, in prolactinomas harbored by lacDrd2KO female mice, not only Notch1 and Notch3 mRNA levels but also NOTCH2-3 membrane and NOTCH1 active domains were highly expressed in knockout mice compared to their control counterparts, the Drd2loxP/loxP mice." (PMID 28915655, 2017).
prostate adenocarcinoma (1 paper, 2016). "In some datasets Notch1 expression was found significantly down-regulated and (TCGA PRAD (Prostate Adenocarcinoma)), while in others it did not appear to change or even to increase." (PMID 27384993, 2016).
prostatic hyperplasia (1 paper, 2024). "Importantly, anti-oxidant N-Acetyl-L-Cysteine (NAC) therapy could alleviate prostatic hyperplasia caused by the over-activation of Notch1 signaling." (PMID 38538986, 2024).
Renal cyst (1 paper, 2022). A fluid filled sac in the kidney. "Genetic deletion of Notch1 or Notch2 resulted in renal cysts by three weeks of age, but ablation of Notch1 or Notch2 simultaneously, or of RBP-J, resulted in renal cysts at birth." (PMID 35055068, 2022).
renal tumors (1 paper, 2012). "Aside from the growth promoting function, we further discovered Notch1 could also stimulate the migration of tumor cells which will definitely facilitate the metastasis of kidney tumors." (PMID 22506064, 2012).
Rickettsia infection (1 paper, 2017). "Together, these findings suggest that miR-200a-3p directly regulates NOTCH1 expression during Rickettsia infection of endothelial cells." (PMID 28698491, 2017).
salivary gland adenoid cystic carcinoma (1 paper, 2023). An adenoid cystic carcinoma arising from the salivary gland. "MYB-NFIB fusion and NOTCH1 mutation are common hallmark genetic events in salivary gland adenoid cystic carcinoma (SACC)." (PMID 36879115, 2023).
salivary gland cancer (1 paper, 2018). A primary or metastatic malignant neoplasm that affects the major or minor salivary glands. "Importantly, the PIK3CA in case 6 and NRAS in case 1 and 3 are rational candidates for off-label targeted treatments and the NOTCH1 mutation in case 1 is eligible for inclusion in an ongoing clinical trial for advanced salivary gland cancers (clinicaltrials.gov identifier: NCT020697309)." (PMID 29731974, 2018).
schistosomiasis (1 paper, 2016). An infectious disease caused by parasitic trematodes of the genus Schistosoma that colonize human blood vessels and release eggs that can cause granulomatous reactions leading to acute (swimmer's itch or acute schistosomiasis syndrome) or chronic disease. "The study revealed that Notch1/Jagged1 signal activation participates in the pathogenesis of liver granulomata and fibrosis in schistosomiasis through the facilitation of SEA-induced macrophage M2 polarization." (PMID 27875565, 2016). "The results indicated that Notch1/Jagged1 signaling might be a novel target for the treatment of patients with schistosomiasis." (PMID 27875565, 2016). "In addition to the previous reports about the effect of Notch1 signaling on the differentiation and activation of T/B cells, this study revealed the possibility that Notch1/Jagged1 signaling might participate in the regulation of macrophage activation and polarization in schistosomiasis." (PMID 27875565, 2016). "Altogether, our present investigation demonstrates that activation of Jagged1/Notch1 signaling regulates SEA-induced macrophage M2 polarization, which exerts a critical role in the pathogenesis of liver granulomata and fibrosis in murine schistosomiasis." (PMID 27875565, 2016).
schwannomatosis (1 paper, 2025). The least frequent form of the rare genetic disorder neurofibromatosis. "Patient 2 had other variants, Notch1 and 2, previously reported in schwannomatosis patients but scored benign based on the ACMG criteria." (PMID 39857711, 2025).
scleroderma (1 paper, 2012). Scleroderma is a rare autoimmune connective tissue disorder characterized by abnormal hardening of the skin and, sometimes, other organs. "Periostin may also contribute to the pathogenesis of scleroderma via the proliferation and recruitment of myofibroblasts, enhancement of Notch1 signaling, and promotion of collagen assembly." (PMID 22911870, 2012). "Additionally, according to recent evidence, periostin may also contribute to scleroderma via the regulation of the Notch1 signaling pathway, another important pathway in skin sclerosis." (PMID 22911870, 2012).
scrub typhus (1 paper, 2024). Scrub typhus is a rare dust mite-borne infectious disease caused by the Orientia tsutsugamushi bacterium and characterized clinically by an eruptive fever which is potentially serious. "Expression of NOTCH1 was not regulated in scrub typhus patients or in infectious disease controls." (PMID 38502427, 2024).
serous ovarian tumors (1 paper, 2014). "In another study, IHC analysis of 10 serous ovarian tumors by others detected expression of Notch1, Jag1 and Dll1 in both cytoplasm and nucleus, and the observed Notch1 protein levels correlated significantly with metastasis in this small cohort." (PMID 25366565, 2014).
small intestinal tumors (1 paper, 2021).
Smith-Magenis syndrome (1 paper, 2026). Smith-Magenis syndrome (SMS) is a complex genetic disorder characterized by variable intellectual deficit, sleep disturbance, craniofacial and skeletal anomalies, psychiatric disorders, and speech and motor delay. "In addition, the closest established episignatures resembling NOTCH1 were found to be KMT2D-related as well as Smith-Magenis syndrome, which is associated with impairment of RAI1." (PMID 41501857, 2026). "Furthermore, cluster analysis using tree and leaf plots unveiled similarities between NOTCH1 and other disorders, notably Lysine Methyltransferase 2D (KMT2D_p.3400–3700) and Smith-Magenis syndrome (SMS_del; 17p11.2) groups." (PMID 41501857, 2026).
Sotos syndrome (1 paper, 2026). Sotos syndrome is a rare multisystemic genetic disorder characterized by a typical facial appearance, overgrowth of the body in early life with macrocephaly, and mild to severe intellectual disability. "Using clustering analyses on the top 500 most significant DMPs for each cohort, the NOTCH1 cohort exhibited the highest proportion of DMP overlap with Sotos syndrome (34%) and Tatton-Brown-Rahman syndrome (TBRS) (25%) in comparison with 99 other episignatures." (PMID 41501857, 2026).
spina bifida (1 paper, 2022). A congenital neural tube defect in which vertebrae are not fully formed. "Our results further support this evidence as Sox9, Notch1, and BMP2/4 gene expression was upregulated at the time of early astrogliosis in spina bifida, and BMP2/4 expression with S100b and Aldh1l1, an early astrocyte markers." (PMID 35782393, 2022). "Furthermore, we present the involvement of Notch1, Sox9, and BMP signaling in NPC cell fate during gestation and their role in self-propelling earlier astrogliosis observed in spina bifida." (PMID 35782393, 2022).
Splenomegaly (1 paper, 2023). Abnormal increased size of the spleen. "NOTCH1 mutations were associated with splenomegaly (P = 0.018, 95% CI 0.039, 0.40)." (PMID 37404899, 2023).
sterility (1 paper, 2016). "In mice, NOTCH1 gain-of-function resulted in reduced male fertility due to failure of spermatogenesis, while immotile spermatozoa and sterility was detected in NEURL1 null mice." (PMID 27079378, 2016).
synovial sarcoma (1 paper, 2020). "Several other genes pertaining to these networks may be dysregulated in synovial sarcoma, including LEF1, AXIN2, TCF7, and FZD homologues in the Wnt/β-catenin, HES1, and NOTCH1 in the Notch, as well as SMO and PTCH in the Sonic Hedgehog pathways." (PMID 32322158, 2020).
T cell deficiency (1 paper, 2020). "Inducible inactivation of Notch1 led to T cell deficiency, which was transplantable when Notch1-deleted hematopoietic cells were engrafted into wild type (WT) recipients, demonstrating the cell autonomous role of Notch1 signaling in specifying T cell differentiation." (PMID 33585446, 2020).
tauopathy (1 paper, 2023). Neurodegenerative disorders involving deposition of abnormal tau protein isoforms (tau proteins) in neurons and glial cells in the brain. "AST was found to mitigate tauopathy and astrogliosis by activating the neuroprotective arm ACE2/Ang1-7/Mas receptor pathway, as well as the neuroprotective proteins PI3K p85/p55 and p35 while inhibiting AngII and the Notch1/NICD/NF-κB pathway." (PMID 38137376, 2023).
thymic tumors (1 paper, 2013). "Notch1 transcript, activated NICD and downstream effectors of NOTCH1 signaling, including MYC and HES1, are all expressed at high levels in R26PR-derived thymic tumors." (PMID 24046360, 2013). "Both overall Notch1 transcript levels and NICD levels were significantly higher in thymic tumors as compared with control thymic tissue." (PMID 24046360, 2013).
tricuspid atresia (1 paper, 2025). Tricuspid atresia is (TA) a rare congenital heart malformation characterized by the congenital agenesis of tricuspid valve leading to severe hypoplasia of right ventricle (functionally univentricular). "Patients in Group 1, the tricuspid atresia group, carried variants in the BMP2, MYH6, NFATC1, NOTCH1, and ZFPM2 genes, which have been reported to be associated with tricuspid atresia." (PMID 41153298, 2025).
trisomy (1 paper, 2016). A chromosomal abnormality consisting of the presence of one chromosome in addition to the normal diploid number. "Importantly, both the NOTCH1 mutated and trisomy 12 sub-clones were detectable at diagnosis using TDR and FISH, respectively, demonstrating the presence of the IGHV5-10-1*01 clone at diagnosis but at a level which was undetectable using standard immunogenetic assays." (PMID 26847028, 2016).
undifferentiated carcinoma (1 paper, 2015). A usually aggressive malignant epithelial neoplasm composed of atypical cells which do not display evidence of glandular, squamous, or transitional cell differentiation. "Additional studies should investigate the role of Notch1 signaling in the pathogenesis of undifferentiated carcinomas." (PMID 25653136, 2015).
urinary system cancers (1 paper, 2023). "Except those frequent mutated genes in urinary system cancers, we also identified other less frequent mutated genes, including CSF1R (37%), NPM1 (37%), EGFR (25.9%), and NOTCH1 (22.2%)." (PMID 37515929, 2023).
uveitis (1 paper, 2025). An inflammatory process affecting a part of or the entire uvea. "The network showed that LXD exerted therapeutic effects upon valuable targets participated in the genesis and development of uveitis, including Notch1, IL-6, IL-2, TNF, and IL-10." (PMID 40918405, 2025). "The pathogenesis of uveitis involves elevated Notch1, DLL4, IL-17A, and RORγt, and decreased levels of miR-30b-5p." (PMID 40918405, 2025). "Additionally, our previous dual luciferase report gene expression assay showed that rno-miR-30b-5p specifically target Notch1 and DLL4, so miR-30b-5p could serve as a promising immunoregulatory approach for the treatment of uveitis." (PMID 40918405, 2025).
Werner syndrome (1 paper, 2024). "By analyzing the molecular alterations in mouse model with accelerated aging phenotypes due to loss of p21 function in a Werner syndrome background, we observed that Wnt3 and β-Catenin were down-regulated, while Notch1 and Hes1 were up-regulated." (PMID 39341834, 2024).
xerostomia (1 paper, 2021). Dryness of the mouth resulting from reduced salivary secretion. "Genetic alterations in BRCA2, ERBB3, NOTCH1 and CCND1 were all associated with higher mean grade of toxicity with BRCA2 alteration implicated in all toxicity parameters evaluated including mucositis, early dysphagia, xerostomia and to a lesser extent, late dysphagia." (PMID 34001187, 2021).
tumor (1,571 papers, 2005 to 2026). "We developed a signature of NOTCH1 activation showing the pathway is associated with very early differentiation, an altered tumor microenvironment, and better prognosis." (PMID 41989846, 2026). "In patients with heavily pretreated GCT, nirogacestat treatment resulted in durable disease stabilisation of at least 7 weeks for 58% of patients, with 21% achieving PFS6, including the 3 patients whose tumours had an activating NOTCH1 mutation." (PMID 41518037, 2026). "To date, most of the literature on Notch1 has focused on its pathogenic role in tumour angiogenesis, 36], demonstrating the need for research investigating the role of Notch1 in healthy individuals." (PMID 40641678, 2025). "Together, these molecular changes alter the phenotype and functionality of mesenchymal stem cells (MSCs), indicating that the IGF2BP2/CSF2/Notch1 pathway plays a role in enhancing tumor-associated traits via epigenetic modulation of the TME." (PMID 41312360, 2025). "Remarkedly, the FGF/FGFR1/NOTCH1 within RB1 variant group has a dramatically higher inner‐tumor CD8+ T cell infiltration, following more CD8+PD‐1‐LAG3‐ non‐exhausted T cells and CD8+PD‐1+LAG3‐ exhausted T cells." (PMID 40001320, 2025). "The role of NOTCH family protein as oncogenes or tumor suppressors is complex; NOTCH1 has also been shown to be a tumor suppressor and overexpressed in association with lymph node metastases in patients with NSCLC." (PMID 40563292, 2025). "With regard to histopathological subtypes, HR-positive/HER2-negative tumours with high NOTCH1 mRNA expression were associated with chemotherapy resistance." (PMID 39153127, 2025). "Majority of these were within regions identified by single variant analyses, with the exception of the well-known tumour suppressor gene NOTCH1 (P-value=6.07×10−7), identified using multi-ancestry meta-analysis." (PMID 40321259, 2025). "Subsequently, we investigated the interaction between Notch1 mutations and tumor infiltration of CD8+ T cells for immune recognition." (PMID 41026775, 2025). "The A3B/NQO tumor with the highest SBS2 mutation burden has normal Notch1 but has acquired somatic mutations in two Notch-pathway associated genes, a translocation involving Fbxw7 and a nonsense mutation in Kmt2d." (PMID 40502742, 2025). "On clinical correlation, it was seen that the TT genotype in Notch1 showed a significant association with increased depth of tumor (p = 0.035)." (PMID 41027955, 2025). "Tumours with high NOTCH1 mRNA expression were associated with high values of uPA and/or PAI-1 (OR 1.9, 95% CI 1.20–2.98, p = 0.006)." (PMID 39153127, 2025). "The transmembrane receptor NOTCH1 was the most recurrently mutated driver gene (n = 112/197), with many tumours having multiple hits (n = 67/112)." (PMID 41419736, 2025). "Although Notch1 signaling has been implicated in tumor immune escape, its underlying mechanism is unclear." (PMID 41271562, 2025). "LOF mutations in NOTCH1, observed in approximately 30–50% of BCCs, are considered to facilitate tumor persistence in sporadic cases." (PMID 40725190, 2025). "Elevated Notch1 expression has been closely associated with lymph node metastasis, tumor stage, depth of infiltration, and histological differentiation in CRC patients." (PMID 41294868, 2025). "Lastly, chromosome 9q cnLOH, including CDKN2A (n = 8/187) and/or NOTCH1 (n = 20/187; mostly mutated for NOTCH1), was identified predominantly in pMMR tumours, and to a lesser extent in dMMR tumours." (PMID 41419736, 2025). "WT/NQO and A3B-E255A/NQO tumor groups exhibit fewer Notch1 mutations and these are all missense mutations predicted to be low impact." (PMID 40502742, 2025). "On clinical correlation, Notch3 (rs1043994) A > G is associated with advanced disease stage in CRC, while Notch1 and Notch4 showed an association with depth of invasion and tumor grade, respectively." (PMID 41027955, 2025).